CRP (C-reactive protein)
Diseases named in the same sentence as CRP in open-access papers (continued):
Sharing a sentence is not in itself a finding about the gene and the disease.
metabolic disorders (continued). "The C-reactive protein-to-albumin ratio (CAR) is an inflammation-based marker with a prognostic value for several metabolic diseases." (PMID 38872964, 2024). "In all, a higher level of IL-38 in patients suggests that they have better ability to interact with the biochemical pathways involved in inflammation and/or metabolic disease complications, which are indicated by abnormal serum levels of hs-CRP and/or HbA1c." (PMID 39156131, 2024). "Of them, alpha-2-antiplasmin (SERPINF2) was positively associated with BMI and C-reactive protein, suggesting that SERPINF2 was a potential therapeutic target in metabolic diseases." (PMID 36797296, 2023). "Elderly MHO population who eat a MedDiet and practice regularly PA are capable to modulate their production of inflammatory cytokines (CRP, IL-6, TNFa) and adipokines profile (adiponectin, resistin), preventing other metabolic disorders." (PMID 35679338, 2022). "CRP is a proinflammatory marker that strongly predicts the development of cardiovascular and metabolic diseases, and it is also elevated in patients with PTSD, who are at greater risk of developing these comorbidities compared to healthy individuals." (PMID 35741825, 2022). "Our ongoing cohort study showed a higher prevalence of pre-metabolic diseases (MetS), lower nutritional status, higher high-sensitivity C-reactive protein (hs-CRP) level, and lower vegetable consumption in Taeeum-type middle-aged Korean adults." (PMID 35911108, 2022). "In children, EGFL6 expression was positively correlated to parameters of AT dysfunction and metabolic disease such as macrophage infiltration into AT, hs-CRP, leptin levels, and HOMA-IR." (PMID 35457174, 2022). "Endocrine, nutritional, and metabolic diseases presented a strong genetic correlation with CRP in the FinnGen cohort." (PMID 34386016, 2021). "Overweight adolescent girls with PCOS and metabolic disorders (MD+/OW) showed higher CRP, leptin, and a two-fold increase in IL-6 and IL-18 concentrations compared to the control group of healthy girls (p < 0.05 for all parameters)." (PMID 32397375, 2020). "Our results found that both men and women with high consumption of the western dietary pattern, low consumption of the prudent dietary pattern, high values of anthropometric parameters or metabolic disorder increased the likelihood of being high CRP or NLR." (PMID 30454030, 2018). "In fact, a number of systematic reviews have shown the association between inflammatory biomarkers, such as CRP, IL-1β, IL-6, TNF-α, IL-4, or IL-10, and cardio-metabolic diseases." (PMID 27527152, 2016). "Given the controversies encountered in the literature on this issue, more studies are needed to further elucidate the relationship of CRP with various metabolic disorders in childhood and adolescence." (PMID 23367494, 2013). "Furthermore, significant inflammatory biomarkers, such as C-reactive protein (CRP), interleukin-6 (IL-6), and tumor necrosis factor-alpha (TNF-α), have been associated with both HT and metabolic disorders." (PMID 40362879, 2025). "Furthermore, the higher sensitivity of hsCRP to validation in comparison with CRP is indicative of its greater importance in the pathogenesis of various metabolic diseases." (PMID 41357322, 2025). "Among these, C-reactive protein (CRP), interleukin-6 (IL-6), and tumor necrosis factor-alpha (TNF-α) are well-recognized markers of systemic inflammation and have been associated with reduced muscle and brain function, and metabolic diseases in older adults." (PMID 40699540, 2025). "UAR and CRP levels may also be influenced by metabolic disorders, chronic inflammation, or medications, highlighting the need to control for confounding factors in future research." (PMID 41323647, 2025). "The association between CRP and reduced stool evenness may be explained by the fact that systemic inflammation, be it related to IBD or metabolic disease, is characterised by reduced gut microbial diversity." (PMID 39408201, 2024).
metabolic disorders (continued). "It was observed that berberine supplementation could reduce CRP amount in patients with metabolic disorders." (PMID 37654997, 2023). "Furthermore, an inverse correlation was observed between the concentrations of iso-BCFAs and serum concentrations of CRP (inflammation marker), insulin and TG (connected with metabolic disorders)." (PMID 37850622, 2023). "CRP is the prototype acute-phase reactant and a hallmark of low-grade systemic inflammation, thus it has been assumed that chronic low-grade systemic inflammation mediates the effect of the GCKR variant on complex metabolic diseases, including NAFLD." (PMID 36904112, 2023). "Second, the retrospective nature of the study limited our ability to measure other measures of metabolic disease, including waist circumference, and visceral adipose tissue, and measures of inflammation, such as C-reactive protein, procalcitonin, and interleukin-6 levels." (PMID 37602105, 2023). "Several studies showed also the association between lipid profile, CRP, uric acid and vitamin D deficit, but the serum 25(OH)D level, predictive for vitamin D deficit-dependent metabolic disorders, has not been strictly defined." (PMID 37152969, 2023). "GrimAge residuals showed associations with a broad range of blood-based biomarkers implicated in age-related disease and premature mortality risk, including inflammation (CRP, WBC, IL-6, and TNF-α), oxidative stress (GGT), neuropathology (GFAP), and metabolic disease (MetS)." (PMID 36153327, 2022). "C-reactive protein (CRP) has been reported to be an inflammatory component of metabolic disorders." (PMID 36289836, 2022). "However, in those who have metabolic diseases, levels of CRP seem to drop faster with increasing vitamin D but slows after reaching vitamin D sufficiency." (PMID 35057447, 2022). "Several serum biomarkers used to evaluate inflammation, such as pro-inflammatory cytokines and C-reactive protein (CRP), are also markers of physiological dysregulation and are used to estimate the risks for various diseases, particularly cardiovascular and metabolic diseases." (PMID 35629167, 2022). "Decreased physical activity itself is a risk factor for low-grade inflammation and development of metabolic disorders; however, despite lower physical activity levels, we did not observe any increase in inflammatory marker CRP." (PMID 33810256, 2021). "Besides, our findings corroborate with our previous results in which high leptin and CRP levels were associated with activated oxidative stress and systemic inflammation in overweight adolescents with PCOS complicated with metabolic disorders." (PMID 32545404, 2020). "Taken together, with evidence of systemic inflammation (elevated CRP levels within the OB and MetS), the current grouping of participants provides a model for assessing the influence of systemic factors at distinct stages of metabolic disease on ADSC function." (PMID 30631282, 2018). "The dominant public health discourse concerning CRP is one of pathology and “chronic inflammation”, yet for at least a decade human biologists working in non-Western populations have found lower CRP than expected, and more complicated relationships between CRP and metabolic disease." (PMID 28003312, 2017). "Prevalence of metabolic disorders according to C-reactive protein categories." (PMID 26193292, 2015). "Correlation of log-CRP levels with clinical characteristics and metabolic disorders." (PMID 26193292, 2015). "Ex-smokers and current smokers had CRP levels significantly higher than the 28.5 nmol/L cut-off indicating high risk for metabolic diseases range and low-grade inflammation (p < 0.001; data not shown)." (PMID 24499114, 2013). "Senior adults have elevated circulating levels of pro-inflammatory cytokines and C-reactive protein (CRP) that could lead to cardiovascular and metabolic diseases, as well as loss of muscle and bone mass, causing a drop in functional fitness and personal autonomy." (PMID 38280022, 2024).
metabolic disorders (continued). "Maternal metabolic disorders have discernible effects on the composition of immune-related components in breast milk, such as immunoglobulins, lactoferrin, leptin, ghrelin, adiponectin, C-reactive protein, growth factors, extracellular vesicles, and lymphocytes." (PMID 38140275, 2023). "CRP, a well-known biomarker for T2DM, shows high scores for text mining, disease association scores, and low novelty, as well as interaction with several identified potential biomarkers and high enrichment for gene terms related to inflammation and metabolic disease." (PMID 37590326, 2023). "Furthermore, recent studies have also suggested that CRP could be considered an independent marker of cardiovascular and metabolic disorders." (PMID 36289836, 2022). "ii)In metabolic diseases (category “b”), non-linear associations were presented in CRP and 25(OH)D." (PMID 32246038, 2020). "In addition, in metabolic diseases, we found that the nonlinear associations of CRP with 25(OH)D had a weakening tendency as 25(OH)D increasing, which is similar with several previous studies." (PMID 32246038, 2020). "Further, we found nonlinearly negative associations of 25(OH)D with CRP in metabolic diseases." (PMID 32246038, 2020). "C-reactive protein (CRP) is a prominent inflammation marker, and has been positively associated with various oxidative stress markers independently of traditional metabolic risk factors even in subjects without metabolic disease." (PMID 28430803, 2017). "Furthermore, given the limitations of CPAP, a measure of CRP may help clinicians determine how to best treat a patient's AHI while also addressing their increased risk for cardiovascular and metabolic disorders." (PMID 28947597, 2017). "HD predominantly influences physiological health through its role in inflammatory response (CRP, IL-6, TNF-α), oxidative stress, and metabolic disorders." (PMID 40191209, 2025). "No anomalies were detected in the complete blood count (CBC), C-reactive protein (CRP), blood gas analysis, liver and kidney function testing, myocardial injury markers, blood sugar, thyroid function, and metabolic disease screening." (PMID 41262921, 2025). "The second family, secreted by the liver, belongs to the acute phase proteins (APPs), such as C-reactive protein (CRP), haptoglobin, or serum amyloid a (SAA), which is well correlated with clinical outcomes and diseases, such as metabolic disorders." (PMID 40002798, 2025). "Future research should employ prospective cohort designs to systematically compare ALI with gold-standard inflammatory biomarkers, such as C-reactive protein (CRP) and interleukin-6 (IL-6), in metabolic disorders." (PMID 40395814, 2025). "Third, although we used CRP, NLR, MetS-Z, and the number of MetS components as surrogate markers for inflammation and metabolic disorder, we acknowledge that inflammation and metabolic disorder are broad concepts." (PMID 38386717, 2024). "Regarding the relationship between inflammation and clinical outcomes, hs-CRP was associated with different outcomes in DM and non-DM patients in our study, which may be attributed to DM being a multifactorial metabolic disease characterized by a state of sub-clinical inflammation." (PMID 37081535, 2023). "As some studies suggested these patients with metabolic disorders may get more benefits from the intervention, for obese and unhealthy subjects tending to accompany with higher levels of inflammatory factors; for instance, CRP is an indicator of general low-grade inflammation." (PMID 34635132, 2021). "Inflammatory markers were WBC, CRP, IL-6 and -8, TNF-alpha and fibrinogen, and comorbidities comprised a broad panel including cardiac and metabolic disorders." (PMID 32601330, 2020). "The multicenter Insulin Resistance Atherosclerosis Study had shown a linear relation between the inflammatory marker C-reactive protein (CRP) and a number of metabolic disorders." (PMID 23533519, 2013).
metabolic disorders (continued). "Second, integration of objective biomarkers of inflammation (e.g., CRP, IL-6, TNF-α) could help clarify mechanistic pathways linking metabolic disease and psychiatric comorbidity." (PMID 41149069, 2025). "However, the predictive role of Nrg4 on metabolic disease, particularly CVD should be compared with other conventional biomarkers such as C-reactive protein (CRP) for further investigations." (PMID 39162358, 2024). "Moreover, supplementation with 25(OH)D can improve metabolic disorders and alleviate inflammatory response of T2DM patients via reducing a number of inflammatory factors such as IL-6, CRP, and TNF-α levels." (PMID 36619542, 2022). "Consistent with the previously reported role of inflammation in this relationship, age was positively correlated with 5 of the 14 immune measures that VSURF selected as important predictors of the metabolic disease score, including LBP, CRP, IL-6, ICAM-1, and SAA." (PMID 34006628, 2021). "Our results failed to prove the independent impact of either PCOS or metabolic disorders on CRP levels in adolescent girls." (PMID 32397375, 2020). "The nonspecific inflammatory marker C-reactive protein (CRP) is more often increased in people who are obese and/or have a metabolic disorder." (PMID 32326591, 2020). "A reduction in CRP levels by MSDK could imply a possible anti-inflammatory role of MSDK, aiding in the bone health and other diseases such as cardiovascular and metabolic disorders as reported." (PMID 28130552, 2017). "All these findings may explain the much greater contribution of metabolic disorders as mediating path between Cumulative SEP and CRP in women as compared to men." (PMID 25309988, 2014). "The present results could suggest that BMI is correlated with CRP levels even in non-obese individuals, and the role of metabolic disorders should be further investigated." (PMID 40565981, 2025). "Therefore, a reduction in CRP would not necessarily mean equivalent reduction in metabolic disease risks or CVD events." (PMID 39199336, 2024). "The group (MD−/NW) was characterized with lower levels of CRP, leptin, MDA, and higher levels of sFasL, when compared to OW patients with PCOS in the absence of metabolic disorders (MD−/OW) (p < 0.05)." (PMID 32397375, 2020). "The group (MD+/OW) was also characterized with higher levels of CRP, leptin, MDA, IL-18, MIF (p < 0.05), when compared to overweight patients with PCOS in the absence of metabolic disorders (MD−/NW)." (PMID 32397375, 2020).
psychiatric disorder (139 papers, 2008 to 2026). A disorder characterized by behavioral and/or psychological abnormalities, often accompanied by physical symptoms. "WBCC was additionally associated with psychiatric disorders and CRP with musculoskeletal disorders too." (PMID 41542670, 2026). "Mendelian randomization analyses showed that chronic pain showed potential causal associations with psychiatric disorders, SUDs, CRP level, and cortical area brain structures." (PMID 40297705, 2025). "In regard to psychiatric disorders, there are a relatively limited number of studies, although the common outcome is confirmation of an association between CRP blood levels and SNPs, further differentiated between homozygotic vs heterozygotic alleles." (PMID 37181328, 2023). "Many studies have investigated the association between serum CRP level and psychiatric disorders, but few focused on the role of mt DNA." (PMID 37344456, 2023). "Causal inference was then implemented to distinguish causation from correlation, with strong evidence that C-reactive protein (CRP) exerts a causal effect on psychiatric disorders." (PMID 35385317, 2022). "Previous studies have typically assessed only serum measures of CRP and IL-6 to investigate the associations between inflammation and psychiatric disorders." (PMID 36277463, 2022). "Many studies have investigated the association between serum CRP level and psychiatric disorder, but few have also included PRS-CRP." (PMID 33517931, 2021). "A recent meta-analysis of 21 observational studies involving 7682 subjects demonstrated how CRP is associated with higher suicidality in patients with mental disorders." (PMID 34884840, 2021). "C-Reactive protein (CRP) is a potential risk factor for psychiatric disorders with undisputed correlational association, but unclear causality." (PMID 28847336, 2018). "Increased levels of pro-inflammatory factors such as C-reactive protein and interleukin-6 receptor, which are associated with psychiatric disease, have been observed during European winters." (PMID 28962597, 2017). "This subsequently reduces the level of pro-inflammatory factors, such as the cytokines TNF-α and IL-1β, chemokines, TLRs, and CRP, helping in alleviating both systemic and neuroinflammation, the latter being the causal factor for most psychiatric disorders." (PMID 24772064, 2014). "Presence of psychiatric disorder at baseline and follow-up was significantly associated with higher peak CRP (p<0.05)." (PMID 25007072, 2014). "It has been revealed in population-based studies that antidepressant use can also be associated with elevated CRP levels, possibly leading to a systemic inflammation independently of the symptoms of mental illness." (PMID 23226388, 2012). "Loci associated with increased risk for chronic pain were also associated with increased risk for multiple other traits, with Mendelian randomization analyses showing that chronic pain was causally associated with psychiatric disorders, substance use disorders, and C-reactive protein levels." (PMID 40297705, 2025). "Similarly, while CRP is an accessible and cost-effective inflammatory marker, its diagnostic precision in differentiating primary psychiatric disorders from inflammation-driven internal diseases requires further validation across diverse populations." (PMID 40218134, 2025). "CRP displayed strong evidence of partial genetic causality on three psychiatric disorders, and, thus, we sought to further analyze these relationships by estimating the total effects and direct impact of CRP using univariable MR and multivariable MR (MVMR), respectively." (PMID 35385317, 2022). "Aside from clinical symptoms of severity, CRP > 200 mg/L or CRP = 50–200 mg/L + allergic to penicillin or CRP = 50–200 mg/L + mandibular molar infection + psychiatric disorder or CRP < 50 mg/L + immunodepression increase the risk to have adverse evolution during hospitalization of more than 25%." (PMID 33266250, 2020).